PPM1K (protein phosphatase, Mg2+/Mn2+ dependent 1K)
Diseases named in the same sentence as PPM1K in open-access papers:
PPM1K is named in the same sentence as 59 diseases in open-access papers, as found by Europe PMC text mining. Sharing a sentence is not in itself a finding about the gene and the disease. The quoted sentences say what the papers report.
maple syrup urine disease (46 papers, 2006 to 2025). An autosomal recessive inherited disorder caused by mutations in the BCKDHA, BCKDHB, DBT, and DLD genes. "These experiments provided conclusive proof that a loss-of-function variant in PPM1K causes a mild phenotype of maple syrup urine disease and is a prime example of the direct effect of genetic variation in a Ser/Thr phosphatase gene on normal cell function." (PMID 36313552, 2022). "Other PPM1K SNPs have been associated with maple syrup urine disease, characterised by the inability to metabolise BCAAs due to branched-chain ketoacid dehydrogenase deficiency." (PMID 35327951, 2022). "Furthermore, PPM1F is a variant of unknown significance in familial intrahepatic cholestasis, and PPM1K has a homozygous association with maple syrup urine disease." (PMID 36313552, 2022). "For instance, in patients with maple syrup urine disease (MSUD), an inborn error of metabolism caused by loss-of-function mutation in components of the BCKD complex or its regulatory phosphatase, PPM1K, BCAA levels in plasma are found to be elevated." (PMID 35931683, 2022). "Mutation of BCKDC and its activator, the mitochondrial isoform of protein phosphatase 1K (PPM1K), result in accumulation of BCAAs and branched-chain α-ketoacids (BCKAs), followed by maple syrup urine disease (MSUD)." (PMID 27376324, 2016).
Obesity (16 papers, 2014 to 2024). Accumulation of substantial excess body fat. "In addition, obesity could inhibit hepatic utilization of BCAAs and cause the inactivation of BCKDH by increasing the ratio of BCKDK (BCKDH kinase)/PPM1K (BCKDH dephosphorylase) in hepatocytes." (PMID 37699892, 2023). "A recent study elucidated a novel association between BCAA metabolism and de novo lipogenesis in rodent models for obesity, involving the regulation of BCKDH by BDK and PPM1K." (PMID 39198298, 2024). "This phenomenon can be reversed by BCAA diet restriction or regulating the BCKDK/PPM1K ratio in mouse models of obesity and insulin resistance." (PMID 37699892, 2023). "Loss of PPM1K in human is associated with a mild form of MSUD while reduced expression of PPM1K is associated with heart failure, obesity and insulin resistance in both human samples and animal models." (PMID 34091011, 2021). "Furthermore, mRNA levels of PPM1K was negatively correlated with BMI as well as with parameters of obesity, like hip and waist circumference." (PMID 32903728, 2020). "Furthermore, links to fatty acid synthesis were discovered, that could be relevant for understanding insulin resistance and obesity, such as the dual action of BDK and PPM1K on both BCKDH complex and ACLY." (PMID 39198298, 2024). "Thus, increased levels of BCAA in plasma from subjects with obesity are likely to be the result of reduced expression of BCAT or decreased BCKD activity via either increased expression of BCKDK or suppression of PPM1K." (PMID 36771236, 2023).
heart failure (11 papers, 2015 to 2025). Inability of the heart to pump blood at an adequate rate to meet tissue metabolic requirements. "Ppm1k-KO mice display deficient BCAA catabolism that promotes heart failure and is associated with induced oxidative stress and metabolic disturbances; however, BT2 significantly mitigated cardiac dysfunction in these mice." (PMID 37752100, 2023). "In animal models, loss of PPM1K expression promoted while PPM1K over-expression attenuated heart failure induced by pathological stressors (including pressure-overload and myocardial infarction) and metabolic challenge." (PMID 34091011, 2021). "Indeed, PPM1K knockout exacerbates while inhibition of BCKDK interaction with BCKDH confers potent amelioration to pressure-overload induced heart failure, highlighting the potential of PPM targeted manipulation as a viable therapeutic strategy for heart failure." (PMID 34091011, 2021).
Insulin resistance (11 papers, 2016 to 2025). Increased resistance towards insulin, that is, diminished effectiveness of insulin in reducing blood glucose levels. "Consistent with recent studies in mice, the expression of PPM1K in muscle biopsies during an oral glucose challenge failed to increase in people with type 2 diabetes, suggesting that the link between insulin resistance and higher BCAA levels may be partly mediated by impaired BCKD activation." (PMID 27898682, 2016).
diabetes (7 papers, 2021 to 2024). "Protein phosphatase 2Cm (PP2Cm) encoded by PPM1K can mediate the BCAA catabolism defect in diabetes." (PMID 37432261, 2023). "PPM1K has been found to be an important regulator of glucose metabolism and diabetes, which also revealed the casual association for type 2 diabetes." (PMID 36984843, 2023).
breast carcinoma (6 papers, 2014 to 2025). "Breast cancer patients with up-regulated PPM1K demonstrated better RFS." (PMID 35785192, 2022). "In breast cancer, for example, invasive tumors showed significantly elevated BCKDK and reduced PPM1K compared to normal tissue, correlating with higher relapse rates." (PMID 41502503, 2025).
type 2 diabetes (6 papers, 2016 to 2023). "At the PPM1K locus, both the lead SNPs in the BCAA association analyses, rs1440581 (r2 = 0.88) and rs7678928 (r2 = 0.70), were in linkage disequilibrium with the lead type 2 diabetes SNP at the locus, rs1975393." (PMID 27898682, 2016). "In muscle biopsies collected during an oral glucose challenge, the expression of PPM1K increased at 2 h in normoglycaemic individuals, but not in age-matched patients with type 2 diabetes." (PMID 27898682, 2016).
leukemia (4 papers, 2014 to 2025). A malignant (clonal) hematologic disorder, involving hematopoietic stem cells and characterized by the presence of primitive or atypical myeloid or lymphoid cells in the bone marrow and the blood. "Inhibition of PPM1K extended the survival time of mice in leukemia models, suggesting that PPM1K could be used in combination with chemotherapy drugs for leukemia to improve treatment efficacy." (PMID 40438606, 2025).
overnutrition (2 papers, 2021 to 2022). An imbalanced nutritional status resulting from excessive intake of nutrients. "On the other hand, overnutrition, and in particular, high-sucrose diets, enhances BCAAs serum levels via the suppression of protein phosphatase Mg2+/Mn2+-dependent 1k (PPM1K), favoring IR and cardiometabolic impairments in obese rats." (PMID 34684432, 2021).
cat-eye syndrome (1 paper, 2012). Cat eye syndrome (CES) is a rare chromosomal disorder with a highly variable clinical presentation. "Other candidate genes highlighted through overlap with results from other studies include: CECR5 in the cat eye syndrome region, RAF1 involved in Noonan syndrome and PPM1K." (PMID 22912587, 2012).
invasive carcinoma (1 paper, 2022). A carcinoma that is not confined to the epithelium, and has spread to the surrounding stroma. "Among the genes involved in the initial 2 shared steps, the mRNA expression of BCAT2 and BCKDK was significantly higher, whereas the expression of PPM1K was lower, in the invasive carcinoma than that in normal breast tissue." (PMID 35785192, 2022).
liver cancer (1 paper, 2025). An epithelial or non-epithelial malignant neoplasm that arises from the liver. "High expression of dephosphorylated BCKDHA and PPM1K promotes tumorigenesis, making BCKDHA and PPM1K potential therapeutic targets and predictive biomarkers for liver cancer." (PMID 40438606, 2025).
morbid obesity (1 paper, 2020). An excess of body weight, normally defined as an individual with a body mass index greater than 35 or a body weight greater than one hundred percent of ideal body weight. "Concomitantly, the inhibitory kinase, BCKDK, was augmented in the obese patients (compared to non-obese) whereas, activating phosphatase PPM1K (protein phosphatase Mg2+/Mn2+ phosphatase) levels were reduced in morbid obesity (compared to both non-obese and pre-obese patients)." (PMID 32903728, 2020).
neuroendocrine disorder (1 paper, 2023). A disease or disorder that affects the neuroendocrine gland, any of the organized aggregations of cells that function as secretory or excretory organs and that release hormones in response to neural stimuli. "Overall, the causal effect may involve two pathophysiological pathways, including glucose metabolism (PPM1K and TRMT61A) related to plaque progression and the newly discovered neuroendocrine disorders (CBLN1, MRPL33, and C2orf16) related to plaque rupture and thrombosis." (PMID 36984843, 2023).
pancreatic adenocarcinoma (1 paper, 2023). "The knockdown of PPM1K markedly promoted the proliferation and migration of pancreatic cancer cells, confirming its role in tumor suppressor activity in pancreatic adenocarcinoma." (PMID 36672423, 2023). "Among these, PPM1K was downregulated in the tissue and peripheral blood of pancreatic adenocarcinoma patients, negatively related to PD-L1 expression and poor prognosis." (PMID 36672423, 2023). "This study reveals the potential clinical utility of PPM1K in tumor immunotherapy and brings about novel insights into the prognostic value of PPM1K in pancreatic adenocarcinoma." (PMID 36672423, 2023). "This study demonstrates the potential clinical utility of PPM1K in tumor immunotherapy and brings about novel insights into the prognostic value of PPM1K in pancreatic adenocarcinoma." (PMID 36672423, 2023). "ROC curves showed that PPM1K had a good predictive value for pancreatic adenocarcinoma." (PMID 36672423, 2023).
pancreatic cancer (1 paper, 2023). "For further validation, we explored the expression of PPM1K in pancreatic cancer cell lines and the immortal pancreatic duct cell line hTERT-HPNE." (PMID 36672423, 2023). "Further knockdown experiments in vitro suggest that the down-regulation of PPM1K can promote the proliferation and migration of pancreatic cancer cells." (PMID 36672423, 2023). "It was suggested that, compared to hTERT-HPNE, PPM1K expression was downregulated in pancreatic cancer cell lines." (PMID 36672423, 2023). "The knockdown of PPM1K markedly promoted the proliferation and migration of pancreatic cancer cells, confirming its role in tumor suppressor activity in PAAD." (PMID 36672423, 2023). "Further, the knockdown of PPM1K can increase the expression of PD-L1 in pancreatic cancer cells." (PMID 36672423, 2023). "After TGF-β treatment for EMT induction, PPM1K expression decreased in pancreatic cancer cell line PANC-1, which suggested that PPM1K was closely related to EMT." (PMID 36672423, 2023).
polycystic ovary syndrome (1 paper, 2024). A disorder that manifests as multiple cysts on the ovaries. "Studies using a PPM1K-deficient mouse model and downregulated PPM1K in human ovarian granulosa cells have shown that PPM1K deficiency results in impaired metabolism of branched-chain amino acids, contributing to polycystic ovary syndrome in females." (PMID 38750582, 2024).
renal fibrosis (1 paper, 2025). A final common manifestation of a wide variety of chronic kidney diseases characterized by glomerulosclerosis and tubulointerstitial fibrosis. "Collectively, these data indicate that PPM1K suppresses the development of renal fibrosis via inhibition of p300 stability and function." (PMID 40588562, 2025). "Taken together, our findings demonstrate that TGFβ signaling increases AKT-mediated phosphorylation and stabilization of p300 by disrupting PPM1K-p300 interaction during renal fibrosis progression." (PMID 40588562, 2025). "Taken together, these results demonstrate that PPM1K expression is inversely correlated with p300 expression and renal fibrosis progression, providing insight into its potential role in renal pathophysiology." (PMID 40588562, 2025). "We found that AKT mediates phosphorylation of p300 at Ser-1834, thereby increasing the stability of p300 upon induction of renal fibrosis, and conversely, phosphatase PPM1K-mediated de-phosphorylation of p300 leads to de-stabilization of p300." (PMID 40588562, 2025). "Conversely, we observed that overexpression of active PPM1K resulted in a reduction in p300 stability and subsequent inhibition of renal fibrosis." (PMID 40588562, 2025). "We also found that, in contrast to the p300 expression, PPM1K decreases during fibrosis progression in the UUO-induced renal fibrosis mouse model." (PMID 40588562, 2025). "In particular, we demonstrated that dissociation of PPM1K from p300 increases p300 stability, which leads to EndMT and renal fibrosis induction." (PMID 40588562, 2025). "Consistently, correlation analysis of p300 and PPM1K expression in the UUO-induced renal fibrosis mouse model revealed an inverse correlation between p300 and PPM1K expression, similar to that observed in CKD patients." (PMID 40588562, 2025). "In this study, we identified increased p300 protein expression and decreased PPM1K expression in FSGS patients with renal fibrosis compared with MCD patients." (PMID 40588562, 2025). "We next examined the roles of PPM1K in renal fibrosis development in vivo." (PMID 40588562, 2025). "We found that PPM1K dissociated from p300 when renal fibrosis was induced." (PMID 40588562, 2025). "To unravel the physiological roles of PPM1K in renal fibrosis, we analyzed the RNA-sequencing dataset of a PPM1K-overexpressing HK2 cell line (GSE212681) and identified reduced expression of fibrosis-related genes such as Col1A1, Col2A1, CTGF, vimentin, and FN1 (Fig. EV3)." (PMID 40588562, 2025). "Moreover, we showed that the AKT-mediated phosphorylation of Ser-1834 of p300 increased the stability of p300 upon renal fibrosis induction, and conversely, PPM1K specifically dephosphorylated p300 at Ser-1834, resulting in a significant reduction in p300 stability and renal fibrosis." (PMID 40588562, 2025). "Based on our finding that PPM1K inhibits AKT-mediated p300 phosphorylation and reduces p300 stability, we aimed to explore its clinical relevance to the development of renal fibrosis." (PMID 40588562, 2025). "Moreover, we observed that PPM1K overexpression attenuated fibrosis and reduced mRNA levels of fibrosis-related genes in a UUO-induced renal fibrosis mouse model." (PMID 40588562, 2025).
Respiratory insufficiency (1 paper, 2020). "Remarkably, PPM1K was found to be the greatest predictor of respiratory insufficiency, particularly in D257A+/+ mitochondria." (PMID 32107436, 2020).
tumor (11 papers, 2020 to 2025). "Furthermore, PPM1K knockdown can enhance the capacity of proliferation and migration in PAAD cells, indicating that PPM1K acts as a tumor suppressor in PAAD." (PMID 36672423, 2023). "PPM1K was found to be downregulated in tumor tissue in Oncomine, TCGA, and GSE 16515." (PMID 36672423, 2023). "For its correlation with the tumor microenvironment and differential expression in both tissue and peripheral blood between tumor and normal control, PPM1K may serve as a prognostic marker or potential target for PAAD therapy." (PMID 36672423, 2023). "Moreover, our study demonstrates that PPM1K participates in tumor immune infiltrates." (PMID 36672423, 2023). "As presented later, PPM1K might play a role in tumor immune infiltration." (PMID 36672423, 2023). "As previously indicated, PPM1K may play a valuable role in both EMT and the tumor immune microenvironment." (PMID 36672423, 2023). "Indeed, in Ppm1k-knockout mice (which have elevated circulating BCAAs due to defective BCAA catabolism), NK cells are better equipped to control tumor growth, evidenced by increased tumor cell apoptosis and slower tumor progression." (PMID 41502503, 2025). "In addition, there are studies showing that BCKDK and PPM1K make up a ChREBP-regulated node that integrates BCAA and lipid metabolism and promotes BCAAs as a material for fat synthesis for fat cells, which provide energy for tumor growth." (PMID 35498541, 2022). "While PPM1K is downregulated in most of the datasets including TCGA+GTEx, Oncomine, GSE 16515, and GSE 74629 (PPM1K is not detected in GSE 28735 and is lower in tumor tissue but not significantly different in GSE15471 and GSE 91989)." (PMID 36672423, 2023). "Knockout of ppm1k in mice led to the accumulation of BCAAs due to impaired BCAA catabolism, increasing infiltrated NK cells and inhibiting tumor growth in the studied animals without affecting tumor cell proliferation and vasculature." (PMID 37637065, 2023).
cancer (9 papers, 2021 to 2025). A tumor composed of atypical neoplastic, often pleomorphic cells that invade other tissues. "Indeed, studies have found that high BCKDK and low PPM1K (indicating suppressed BCAA catabolism) are associated with more aggressive cancers and poorer patient survival." (PMID 41502503, 2025). "Preclinical studies in HCC have also shown that turning BCKDH “back on” (via BCKDK inhibition or PPM1K activation) can suppress cancer aggressiveness." (PMID 41502503, 2025). "We also explored the mRNA expression of PPM1K, and the results were aligned with the conclusions drawn from the public databases that PPM1K expression is lower in cancer cell lines than in pancreatic duct cell lines." (PMID 36672423, 2023). "PPM1K is reported to be an important metabolic regulator, a protein involved in cancer metabolic reprogramming of branched-chain amino acids (BCAAs), and has been found to be associated with some diseases including type 2 diabetes and colorectal cancer." (PMID 36672423, 2023).
metabolic disorder (7 papers, 2014 to 2025). "Here, we aim to investigate the mechanism of protein phosphatase Mg2+/Mn2+ dependent 1 K (PPM1K) mediates metabolic disorder of branched-chain amino acids (BCAA) by promoting fatty acid oxidation led to ferroptosis after cerebral I/R injury." (PMID 37752100, 2023). "Collectively, these results confirm that PPM1K mediated-BCKDHA S293 phosphorylation contributed to BCAA metabolic disorder 24 h after cerebral I/R and could be ameliorated by BT2." (PMID 37752100, 2023). "The BDK : PPM1K ratio is believed to be a bioindicator of DNL and metabolic disorder phenotype, and the ratio can be increased by ChREBP." (PMID 34512784, 2021).
cardiovascular disease (3 papers, 2021 to 2023). "Moreover, recent studies have confirmed that protein phosphatase 1K (Ppm1k) can elevate the risk of cardiovascular disease." (PMID 36312255, 2022). "We noticed that six DEPs (Pltp, Pir, Thbs1, Tmem70, Hacd2, and Ppm1k) closely related to cardiovascular disease were either significantly downregulated or upregulated." (PMID 36312255, 2022).
infection (2 papers, 2020 to 2025). The state of being infected such as from the introduction of a foreign agent such as serum, vaccine, antigenic substance or organism. "The decreased expression of PPM1K may indicate that BCAA utilization and degradation capacity can be reduced under NE infection in chickens; PPM1K can act more sensitively than the BCKDH kinase (BCKDK) and BCKDH enzymes involved in BCAA catabolism do." (PMID 41007887, 2025).
kidney disease (1 paper, 2022). "However, the research on the mechanism of the important role of PPM1K in kidney disease is still limited." (PMID 36386814, 2022).
PPM1K also shares sentences with these, for which no sentence is quoted: cardiac hypertrophy (5 papers); cardiomyopathy (4); Hepatic steatosis (3); hepatocellular carcinoma (3); myocardial infarction (3); cardiac diseases (2); genetic disorder (2); malaria (2); sarcopenia (2); Sepsis (2); atherosclerosis (1); autism (1); breast tumor (1); Cerebral ischemia (1); colorectal cancer (1); diabetic cardiomyopathy (1); epilepsy (1); glucose metabolism disorder (1); glycine encephalopathy (1); Hyperglycemia (1); hypertrophy (1); infarction (1); Intellectual disability (1); lipodystrophy (1); metabolic acidosis (1); metabolic syndrome (1); neurological disorders (1); Noonan syndrome (1); nutritional deficiency (1); ovarian carcinoma (1).
A further 4 diseases each share a sentence with PPM1K in 1 paper.